CXCL1 (C-X-C motif chemokine ligand 1)
Diseases named in the same sentence as CXCL1 in open-access papers (continued):
Sharing a sentence is not in itself a finding about the gene and the disease.
tumor (continued). "On the basis of Oladipo and collaborators’ immunohistochemistry results of CRC FFPE samples (n = 254), CXCL1 protein level was significantly elevated in tumor tissue samples compared to normal adjacent tissue samples." (PMID 26208990, 2015). "CXCR2+ and/or CCR2+ MDSCs are recruited to the tumor microenvironment by at least GM-CSF, CXCL1 and IL-8 chemotaxis." (PMID 26690220, 2015). "Having demonstrated the importance of STAT3-mediated repression of CXCL1 in tumour cells in vitro and in vivo, we set out to mechanistically interrogate this pathway further." (PMID 25734337, 2015). "Analysis of the human CRC tumor microenvironment by immunofluorescence revealed co-localization of CXCL1 protein expression with tumor myofibroblasts, which expressed α-smooth muscle actin." (PMID 26104296, 2015). "CXCL1, CXCL2 and CXCL3 are positively associated with tumor associated angiogenesis and depletion of these three chemokine factors have inhibited the tumor growth in mice." (PMID 26303932, 2015). "We also tried to validate CXCL1 as a therapeutic target by blocking CXCL1 signalling in established tumours." (PMID 25734337, 2015). "At the molecular level, impaired tumor growth in the three PDXs treated with p38 MAPK inhibitor correlates with downregulation of the chemokines CXCL-1 and CXCL-2 and the cytokine IL-6, which are all known to play key roles in colon tumorigenesis." (PMID 25890501, 2015). "Chemokines, including chemokine (C-X-C motif) ligand 1 (CXCL1), regulate tumor epithelial-stromal interactions that facilitate tumor growth and invasion." (PMID 26543745, 2015). "In summary, our results suggest that STAT3 represses NF-κB-dependent CXCL1 expression by sequestering NF-κB in the cytoplasm and mechanistically delineate a novel tumour-suppressive pathway governed by the STAT3–NF-κB–CXCL1 axis." (PMID 25734337, 2015). "A literature survey quickly revealed that CXCL1 down-regulation inhibits tumor growth in colorectal liver metastasis." (PMID 26161641, 2015). "Recent studies have shown that breast CAFs overexpress the chemokine CXCL1, a key regulator of tumor invasion and chemo-resistance." (PMID 26252654, 2015). "In FOXM1 transgene model, elevated tumor formation was associated with persistent pulmonary inflammation, macrophage infiltration and increased expressions of CXCL5, CXCL1 and CCL3." (PMID 25788272, 2015). "Western blot analysis showed a significant decrease in CXCL1 and iNOS levels in tumor lysates of αPD-1 blockade group as compared with vehicle only group." (PMID 26573233, 2015). "Expression levels of multiple genes encoding for cytokines or cytokine receptors over-expressed in tumor cells or ascites fluid, such as CXCL1, CXCL2, CXCL3, IL8, IL6, IL6R, and CXCR4 were reduced in OV3/COX1KD cells." (PMID 25972361, 2015). "While baseline protein levels of VEGF were similar between MOC tumors, baseline CXCL1 was significantly higher in the MOC2 tumor microenvironment (p < 0.001)." (PMID 26506415, 2015). "We further confirmed increased expression of PD-1, PD-L1 with CCL2 and CXCL1 in the tumor lysaytes of 2cKO mice as compared with syngeneic counterparts." (PMID 26573233, 2015). "Inflammatory cytokines such as CXCL1/GROα exert cancer-promoting activities by increasing tumor angiogenesis." (PMID 25814785, 2015). "Because tumor cell inoculation induced CXCL1 increase in spinal astrocytes, we then examined astrocytes activation by checking GFAP expression in the spinal cord." (PMID 24580964, 2014). "Using this model, our study demonstrated first that CXCL1 was dramatically increased in activated astrocytes in the spinal cord after tumor cell inoculation." (PMID 24580964, 2014). "When naive mice were inoculated with tumor cells, IFN-γ and sTNF-α cooperated with CXCL1 to more efficiently suppress tumor growth." (PMID 25587026, 2014). "We also evaluated the role of NFκB in CXCL1 production and pain hypersensitivity after tumor cell inoculation." (PMID 24580964, 2014).
tumor (continued). "In our study, intrathecal injection of CXCL1 neutralizing antibody at 7 days after inoculation attenuated tumor cell inoculation-induced mechanical allodynia and heat hyperalgesia." (PMID 24580964, 2014). "We then inoculated pG/pI6-mice with H22 tumor cells, and treated the mice by local expression of CXCL1/IFN-γ/sTNF-α and the injection of normal NK cells." (PMID 25587026, 2014). "We then compared the neutrophils from the tissues at tumor inoculation site after local expression of CXCL1/IFN-γ/sTNF-α in naive mice and pG/pI6-mice." (PMID 25587026, 2014). "During DNIIR tumor progression, both the levels of CXCL1/5 and the number of CD11b+Gr1+ cells and T cells decreased." (PMID 25280532, 2014). "Tumor cell inoculation also produced CXCL1 upregulation in activated astrocytes in the spinal cord for more than 21 days." (PMID 24580964, 2014). "Tumor cell inoculation induced a marked increase of CXCL1 expression in the ipsilateral spinal cord at 7 days, 14 days, and 21 days." (PMID 24580964, 2014). "In this study, CXCL1 mRNA and protein was progressively increased in 21 days after tumor cell inoculation, indicating CXCL1 play distinct roles in different pain conditions." (PMID 24580964, 2014). "The other selected gene was the chemokine CXCL-1, which promotes chemotaxis in different cell types such as stromal-epithelial and host-tumor cells, and consistently, is involved in metastasis, tumor progression and chemotherapy resistance and survival." (PMID 24344116, 2014). "While stromal CXCL1 protein expression correlated with tumor grade, significant levels of stromal CXCL1 RNA expression was observed only in high grade tumors." (PMID 25344051, 2014). "Our present study showed that CXCL1 was produced by spinal astrocytes after tumor cells inoculation." (PMID 24580964, 2014). "When naive mice were inoculated with tumor cells, the therapeutic effect of CXCL1/IFN-γ/sTNF-α was attenuated by depleting NK cells, but recovered by administrating NK cells." (PMID 25587026, 2014). "It is possible that CXCL1 expression in CAFs is retained or further elevated after chemotherapy treatment, serving to promote the survival and selection of chemo-resistant tumor cells." (PMID 25344051, 2014). "The statistical analysis of CXCL1-immunoreactive (IR) intensity showed a gradual increase from 7 days to 21 days after tumor cell inoculation (P <0.001)." (PMID 24580964, 2014). "Expression of CXCL1 was positive in the tumor epithelium and stroma, consistent with DAB expression patterns." (PMID 25344051, 2014). "While recent studies have shown that the CXCL1 chemokine is expressed in tumor epithelial cells and stromal cells, the relevance of stromal CXCL1 expression has remained poorly understood." (PMID 25344051, 2014). "Controlling the levels of cytokines including CXCL1 is important for controlling immune cell infiltration, and ultimately in vivo tumor growth." (PMID 23408941, 2013). "Conversely, in tumor tissue, varying CXCL1 expression was found in both epithelial and stromal components of the tissue." (PMID 23815949, 2013). "The IL-8 contributes the angiogenesis proper (the sprouting of pre-existing capillaries), while CXCL1 supports the recruitment of the bone marrow-derived progenitor cells to the tumor neovasculature." (PMID 24391862, 2013). "CCL20 and CXCL1 are involved in tumor growth and TNFAIP6 can regulate the growth of smooth muscle cells." (PMID 23028973, 2012). "It must be noted however, that expression of many of the chemokines were most often found to be downregulated in the NSCLC tumours as follows CXCL1 (64.9%, p<0.01), CXCL2 (81.1%, p<0.01), CXCL3 (59.5%)." (PMID 21298036, 2011). "Accordingly, our IHC results confirmed that this up-regulation resulted from tumor cells as we detected intense CXCL1 and CXCL5 staining signals in CRC and CRLM specimens mainly concentrated in the epithelial cells of these tissues." (PMID 18578857, 2008).
tumor (continued). "The results of ELISA and qRT-PCR assay revealed that tumor debris stimulation and engulfment remarkably elevated the expression of CXCL1/2 and CFB in mouse bone marrow–derived macrophages (BMDMs), whereas intact tumor cell treatment exerted less effect on CXCL1/2 or CFB production." (PMID 41480760, 2026). "Phagocytosis of tumor debris by macrophages contributes to CXCL1/2 and CFB elevation and NETosis." (PMID 41480760, 2026). "The protein CTSC in tumor debris induces CXCL1/2 and CFB expression." (PMID 41480760, 2026). "Mechanistically, the cathepsin C in tumor debris generated by anticancer therapy is phagocytosed by macrophages and drives CXCL1/2 and complement factor B production via activating the TLR4/NF-κB signaling pathway, subsequently promoting NETosis and impairing therapeutic efficacy." (PMID 41480760, 2026). "Their polarization is shaped by ELR+ CXC chemokines (CXCL1, CXCL8), cytokine signals, systemic inflammation, hypoxia driven by VHL/HIF pathways, and tumor-intrinsic oncogenic alterations such as PTEN loss, ERβ- and c-Myc-dependent programs, as well as epigenetic remodeling." (PMID 41705247, 2026). "The expression of CXCL1/2 or CFB was markedly elevated in macrophages that had engulfed GFP+ tumor." (PMID 41480760, 2026). "The dual role of neutrophils in cancer is recognized, with either anti-tumor effects, such as growth of tumor-associated microbiota limitations and metastasis suppression in experimental CRC, or tumor progression and metastasis support via the CXCL1/CXCR2 chemokine axis activation." (PMID 41283264, 2025). "Furthermore, collagen type 1 (COL1) derived from CAFs induces tumor cells to secrete CXCL1, establishing a positive feedback loop; notably, COL1 can also enhance radioresistance by facilitating DNA repair." (PMID 40134607, 2025). "Moreover, Fusobacterium nucleatum stimulates tumor cells directly, as infection of human colorectal cell lines induces robust secretion of pro-metastatic cytokines, including IL-8 and CXCL1, which drive epithelial migration, invasion, and metastatic potential." (PMID 41154402, 2025). "Furthermore, F. nucleatum can stimulate tumor cells to secrete multiple cytokines and chemokines, including IL-8 and CXCL1, thus enhancing tumor growth and metastasis." (PMID 40248690, 2025). "CXCL1 is involved in diverse biological processes, including inflammation, angiogenesis and cell migration, and plays a prominent role in the development of inflammatory diseases and tumour progression." (PMID 41165410, 2025). "In this context, tumor cells with high IL-7R expression may co-opt IL-7 signaling to promote the enrichment of immunosuppressive TAM via CXCL1-dependent mechanisms; this process counteracts the potential immunostimulatory effects of IL-7." (PMID 41360767, 2025). "By analyzing the ligands corresponding to chemokine target genes expressed in immune cells, we found that the chemotactic response of immune cells was mediated by the expression of NRG1 and HMGB1 ligands on Tum_1 tumor cells, which interacted with the CXCL1 target on APOE+ macrophages." (PMID 40470730, 2025). "CXCL1 plays a critical role in cancer progression by directly affecting tumor cells." (PMID 40427171, 2025). "Additionally, TRAF3IP2 also contributes to stabilizing the mRNA of CXCL1, which is involved in the angiogenesis, inflammatory response, and tumor formation." (PMID 40455858, 2025). "Indeed, monocytes/macrophages, neutrophils, and Tregs can be recruited to the tumor via CXCL1 and CCL5 chemokines, the genes for which contain hypoxia-response element sequences." (PMID 40095115, 2025). "Finally, CXCL1 induces the recruitment of neutrophils, which can induce radioresistance, into the tumor niche." (PMID 40427171, 2025). "Additionally, Tosti showed that IL22-induced secretion of CXCL1 promotes anti-tumor neutrophil chemotaxis to the TME in CRC cells." (PMID 40083557, 2025). "MDSCs undergo expansion through CXCR-mediated recognition of tumor-derived CXCL1/2/3." (PMID 40948940, 2025).
tumor (continued). "M1069 suppressed tumor-promoting chemokines, such as CXCL1 and CXCL5, and the myeloid-driven VEGF." (PMID 41583489, 2025). "Following LDHC knockdown, we observed an increase in the secretion of tumor-derived pro-inflammatory cytokines (IFN-γ, GM-CSF, MCP-1, CXCL1), a decrease in the soluble levels of tumor-derived immunosuppressive factors (IL-6, Gal-9) and reduced tumor cell surface PD-L1 expression." (PMID 40108668, 2025). "Specifically, CXCL1 is highly expressed in high-grade and high-stage tumor tissues." (PMID 41445742, 2025). "Further suppressing anti-tumor immune responses, VIRMA also controls the m6A modification levels of chemokines and inflammatory cytokines (like CXCL1 and IL-6), which encourages the growth of myeloid-derived suppressor cells (MDSCs) and regulatory T cells (Tregs) in the tumor microenvironment." (PMID 39911396, 2025). "Thus, chemokines such as CX3CL1, CCL5, and CXCL1 are involved in the actions of EVs-mediated premetastatic niche formation, enhanced tumor invasion, and modulated immune responses." (PMID 40103824, 2025). "Fusobacterium nucleatum may induce the tumor-derived chemokine CXCL1, which recruits myeloid-derived suppressor cells (MDSCs), thereby reducing T cell abundance in the tumor microenvironment and inhibiting antitumor immunity." (PMID 40297806, 2025). "Moreover, CXCL1 secretion by CAFs mediates radioresistance through the activation of the Mek/Erk pathway, reinforcing the tumor’s resistance to radiation." (PMID 40134607, 2025). "CXCR2 ligands, including CXCL1, play a role in tumor immune evasion." (PMID 40427171, 2025). "Moreover, these signaling molecules have been associated with PDAC immune evasion, lending credence to a racially unbalanced CXCL1/5-signaling “tumor-friendly” environment." (PMID 39989973, 2025). "However, its effect on proliferation varies depending on the tumor type; in cholangiocarcinoma, CXCL1 has been shown to suppress cancer cell proliferation." (PMID 40427171, 2025). "Mechanistically, CXCL1 could recruit various stromal cells into the tumor environment to create a premetastatic niche to facilitate cancer growth, angiogenesis, and metastasis." (PMID 41255573, 2025). "CXCL1 plays a significant role in CRC by promoting tumor progression through several mechanisms." (PMID 40791849, 2025). "Chemokines like CXCL-8 and CXCL1/2/5 in the tumor microenvironment attract neutrophils to infiltrate late-stage tumors, where they release reactive oxygen species (ROS) to induce DNA damage and secrete vascular endothelial growth factor (VEGF) to accelerate angiogenesis." (PMID 40626716, 2025). "CXCR2 is not only activated by CXCL1 but also by several other CXC chemokines, including CXCL2, CXCL3, CXCL5, CXCL6, and CXCL8, all of which are closely associated with cancer progression and the tumor microenvironment." (PMID 40490643, 2025). "Signals from the tumor microenvironment, such as reduced TGF-β signaling, activation of NF-κB and STAT3 pathways, or stimulation by oncostatin M from tumor-associated macrophages and neutrophils, strongly upregulate CXCL1 expression in iCAFs." (PMID 40940809, 2025). "In addition, tumor cell‐expressed HVEM altered chemokine expression (CXCL1/9/10/11 and CCL2/4/5) and STAT signal activation (STAT5 and STAT6) in ID8 cells." (PMID 40105652, 2025). "HNSCC: Patients who received Met before surgery had enhanced tumor infiltration of NK cells, which inhibited the CXCL1 pathway, while stimulating the STAT1 pathway within HNSCC NK cells, which enhanced NK cytotoxicity and prolonged overall survival when combined with chemoradiotherapy." (PMID 40161377, 2025). "Similarly, TAM derived CXCL7 and CXCL1 recruit and activate neutrophils, and in addition they promote angiogenesis, induce epithelial to mesenchymal transitioning, and promote tumor cell migration." (PMID 40176808, 2025).
tumor (continued). "Notably, among these pro‐tumor factors, we found two secreted chemokine genes, Cxcl1 and Cxcl12, were consistently down‐regulated in the Mg‐CaCO3 group (relative expression level of group V: Cxcl1: 0.1757, Cxcl12: 0.1154)." (PMID 38757665, 2024). "CRIP1 expressed in tumor cells promotes the infiltration of MDSCs via CXCL1/5-CXCR1/2 signaling, and the inhibition of CXCR1/2 decreases the recruitment of MDSCs and enhances the antitumor effect of PD-L1 treatment to improve resistance to immune-checkpoint blockers(ICBs)." (PMID 38982491, 2024). "Moreover, studies in a mouse model of PDAC have demonstrated the crucial role of CXCL1 released by tumor cells in diminishing the CD8+ T cell population." (PMID 39420203, 2024). "CXCL1 plays an important role in the development of this tumor." (PMID 38673949, 2024). "The level of CXCL1 expression in tumors correlates with tumor stage." (PMID 38673949, 2024). "In half of the cases, CXCL1 expression is also found in blood vessels in the tumor." (PMID 38673949, 2024). "Furthermore, the CXCL1 gene exerts a profound influence on inflammation, immune responses, and tumor progression." (PMID 38745005, 2024). "Notably, a decrease in CXCL1 expression level was observed in the tumour tissue of the GW4869 treatment group." (PMID 39051750, 2024). "CXCL1 can promote tumor growth by stimulating the proliferation of cancer cells." (PMID 39057432, 2024). "By inhibiting CXCL1 signaling, it may be possible to impede tumor growth, metastasis, and immune suppression, ultimately improving patient outcomes in various types of cancer." (PMID 39057432, 2024). "It remains undetermined how primary tumor-derived CXCL1, not premetastatic niche-derived factors, induces MDSCs to accumulate in the liver, and whether tumor-derived VEGF is the major driver of macrophage expression of CXCL1 in vivo." (PMID 38786066, 2024). "They suggested primary tumor produced VEGF that activated macrophages to produce CXCL1." (PMID 38786066, 2024). "Furthermore, this series of works has the potential to stimulate interest in research concerning the role of CXCL1 in tumor processes." (PMID 38673949, 2024). "The expression of miR-141 in tumour cells decreases and the production of CXCL1 increases during MPE development, and miR-141 recruits Tregs into MPE via CXCR2, resulting in an enhanced immunosuppressive effect of Tregs that promotes the immune escape of tumour cells and exacerbates MPE formation." (PMID 38475858, 2024). "The accumulation of MDSCs in the liver was not mediated by liver-derived chemoattractants but by CXCL1 produced by primary tumor-associated macrophages." (PMID 38786066, 2024). "Interestingly, CXCL1 knockdown significantly inhibited tumor growth compared with the control group, and combined treatment with PD-1 antibody further inhibited tumor growth." (PMID 38510750, 2024). "CXCL1 causes the recruitment of neutrophils into the tumor niche; these cells express myeloperoxidase (MPO) and Fas ligand (FasL), which inhibits the anti-tumor effect of lymphocytes." (PMID 38673949, 2024). "Previous studies have reported that the CXCL1/CXCR2 axis is involved in tumor immune evasion." (PMID 38510750, 2024). "Furthermore, we found that CXCL1 was involved in the regulation of the tumor immune environment and PD-1 antibody responsiveness of CRC." (PMID 38510750, 2024). "CXCL1 is also responsible for angiogenesis in the tumor of this cancer." (PMID 38673949, 2024). "Additionally, a high CXCL-1 level in the stroma was correlated with perineural invasion, the tumor classification, and the TNM stage." (PMID 38540782, 2024). "CXCL1 may also affect cancer-associated fibroblasts (CAF), leading to the senescence of these cells and their transformation into cells that support tumor development." (PMID 38673949, 2024).